DESI2 (desumoylating isopeptidase 2)
Description:
Has deubiquitinating activity towards 'Lys-48'- and 'Lys-63'-linked polyubiquitin chains. Deubiquitinates 'Lys-48'-linked polyubiquitination of RPS7 leading to its stabilization. Exhibits palmitoyl protein thioesterase (S-depalmitoylation) activity towards synthetic substrates 4-methylumbelliferyl-6-S-palmitoyl-beta-D-glucopyranoside and S-depalmitoylation probe 5 (DPP-5).
Synonyms: DeSI-2; C1orf121; FAM152A; PPPDE1; CGI-146; PNAS-4; FLJ21998
Tractability: PROTAC: ubiquitination databases record sites on it; its protein half-life has been measured.
Gene: Protein-coding gene on chromosome 1 (244,653,091 to 244,709,033, forward strand). Ensembl gene ENSG00000121644.
Subcellular location: Cytoplasm
Subcellular location (Human Protein Atlas): Vesicles
Gene Ontology:
Molecular function: cysteine-type deubiquitinase activity; K48-linked deubiquitinase activity; K63-linked deubiquitinase activity; long-chain fatty acyl-CoA hydrolase activity; palmitoyl-(protein) hydrolase activity; protein binding; deubiquitinase activity; peptidase activity
Biological process: macromolecule depalmitoylation
Cellular component: cytoplasm
Genetic constraint (gnomAD): Loss-of-function variants: 3 observed, 9.56 expected, observed/expected ratio (o/e) 0.31, 90% interval 0.14 to 0.81. That is too few expected variants to judge how well the gene tolerates losing a copy. Missense variants: 81 observed, 115.13 expected, observed/expected ratio (o/e) 0.7, 90% interval 0.59 to 0.85. Synonymous variants: 47 observed, 48.77 expected, observed/expected ratio (o/e) 0.96, 90% interval 0.76 to 1.23.
Homologues: Orthologues: chimpanzee DESI2 (100% identical), macaque DESI2 (99% identical), dog DESI2 (99% identical), guinea pig DESI2 (98% identical), rabbit DESI2 (98% identical), mouse Desi2 (97% identical), pig DESI2 (90% identical), zebrafish desi2 (82% identical), rat Desi2 (81% identical), tropical clawed frog cox20 (59% identical), Drosophila melanogaster CG7222 (55% identical). Paralogues in human: DESI1 (26% identical).
Diseases named in the same sentence as DESI2 in open-access papers:
DESI2 is named in the same sentence as 8 diseases in open-access papers, as found by Europe PMC text mining. Sharing a sentence is not in itself a finding about the gene and the disease. The quoted sentences say what the papers report.
pancreatic cancer (3 papers, 2014 to 2022). "In pancreatic cancer cells, DESI2 overexpression leads to upregulation of Ras homolog gene family member A (RhoA) and Rho‐associated protein kinase, proteins which are known to be involved in stress fiber formation." (PMID 35943635, 2022). "DESI2 is a pro-apoptotic gene; in vitro experiments have shown that its overexpression induces apoptosis in pancreatic cancer and other tumour cells, which can effectively inhibit the proliferation of some cancer cells." (PMID 30410073, 2018).
colorectal cancer (1 paper, 2017). A primary or metastatic malignant neoplasm that affects the colon or rectum. "DESI2 combined with IP10 further enhanced the apoptosis in colorectal cancer and lung adenocarcinoma cancer cells, as indicated by MTT, colony-formation assays, flow cytometric analysis and Hoechst 33258 staining." (PMID 28915590, 2017).
leukemia (1 paper, 2025). A malignant (clonal) hematologic disorder, involving hematopoietic stem cells and characterized by the presence of primitive or atypical myeloid or lymphoid cells in the bone marrow and the blood. "Moreover, through a compound screen, followed by chemical proteomics and compound optimization, WWQ-03-012 is discovered, which selectively degrades mutant JAK2, induces primary leukemia cells death, and inhibits MPN progression through targeting DESI2 enzymatic activity in vitro and in vivo." (PMID 41332324, 2025).
lung adenocarcinoma (1 paper, 2022). A carcinoma that arises from the lung and is characterized by the presence of malignant glandular epithelial cells. "Or the desumoylating isopeptidase 2 (DESI2), which induces apoptosis in lung adenocarcinoma cells when overexpressed." (PMID 35943635, 2022).
cancer (3 papers, 2014 to 2018). A tumor composed of atypical neoplastic, often pleomorphic cells that invade other tissues. "Previous studies have shown that DESI2 is a pro-apoptotic gene, and that it significantly induces apoptosis when overexpressed in some types of cancer cells." (PMID 28915590, 2017). "More importantly, elevated expression of DESI2 could induce apoptosis of many types of cancer cells such as lung and colon cancer cells." (PMID 28915590, 2017).
tumor (2 papers, 2017 to 2018). "We found that, in both CT26 and LL2 tumor models, either DESI2 or IP10 significantly inhibited tumor growth." (PMID 28915590, 2017). "Consistent with the enhanced tumor suppressive activity in vitro, DESI2 combined with IP10 showed a significantly improved antitumor efficacy in vivo." (PMID 28915590, 2017). "Gene therapy using DESI2 and IP10 significantly inhibits tumour growth and effectively prolongs the survival of tumour-bearing mice." (PMID 30410073, 2018). "As expected, RT-PCR results clearly showed that exogenous DESI2 and/or IP10 were overexpressed in CT26 and LL2 tumor tissues, indicating that liposomal delivery of exogenous DESI2 and/or IP10 genes indeed arrived and expressed within the tumor tissues." (PMID 28915590, 2017). "The observations that co-expression of DESI2 and IP10 displays improved antitumor efficacy in vivo raised a question if DESI2 and/or IP10 gene actually expressed in the tumor tissues." (PMID 28915590, 2017). "In summary, our data showed that co-expression of DESI2 and IP10 could effectively suppress tumor cells through inducing apoptosis, suppressing angiogenesis and triggering a CTL response." (PMID 28915590, 2017).
DESI2 also shares sentences with these, for which no sentence is quoted: pancreatic ductal carcinoma (1 paper); skin cancer (1).